SEMA4G (semaphorin 4G)
Description:
Cell surface receptor for PLXNB2. May play a role in axon guidance (By similarity).
Synonyms: KIAA1619; FLJ20590
Tractability: Antibody: UniProt places it where antibodies can reach, with medium confidence; UniProt predicts a signal peptide or a membrane-spanning region; its Gene Ontology location is reachable by antibodies, with medium confidence. PROTAC: its protein half-life has been measured.
Gene: Protein-coding gene on chromosome 10 (100,969,498 to 100,985,871, forward strand). Ensembl gene ENSG00000095539.
Subcellular location: Cell membrane
Subcellular location (Human Protein Atlas): Lipid droplets; Vesicles
Gene Ontology:
Molecular function: protein binding; chemorepellent activity; neuropilin binding; semaphorin receptor binding
Biological process: axon guidance; negative chemotaxis; neural crest cell migration; positive regulation of cell migration; semaphorin-plexin signaling pathway
Cellular component: plasma membrane
Genetic constraint (gnomAD): Loss-of-function variants: 58 observed, 81.55 expected, observed/expected ratio (o/e) 0.71, 90% interval 0.57 to 0.88. The upper end of that interval is the gene's LOEUF score, 0.88, which puts it in group 3 of 6, group 1 being the genes least tolerant of losing a copy. Missense variants: 951 observed, 1,127.9 expected, observed/expected ratio (o/e) 0.84, 90% interval 0.8 to 0.89. Synonymous variants: 404 observed, 448.23 expected, observed/expected ratio (o/e) 0.9, 90% interval 0.83 to 0.98.
Homologues: Orthologues: chimpanzee SEMA4G (99% identical), macaque SEMA4G (99% identical), dog SEMA4G (93% identical), pig SEMA4G (93% identical), rabbit SEMA4G (92% identical), rat Sema4g (92% identical), mouse Sema4g (91% identical), guinea pig SEMA4G (89% identical), tropical clawed frog sema4g (53% identical), zebrafish sema4ga (50% identical), zebrafish sema4gb (44% identical). Paralogues in human: SEMA4C (38% identical), SEMA4B (33% identical), SEMA4D (31% identical), SEMA4F (29% identical), SEMA4A (28% identical), SEMA3A (28% identical), SEMA3D (27% identical), SEMA3G (27% identical), SEMA3B (27% identical), SEMA3F (26% identical), SEMA3E (25% identical), SEMA5B (24% identical), and 7 more.
Diseases named in the same sentence as SEMA4G in open-access papers:
SEMA4G is named in the same sentence as 17 diseases in open-access papers, as found by Europe PMC text mining. Sharing a sentence is not in itself a finding about the gene and the disease. The quoted sentences say what the papers report.
glioma (3 papers, 2020 to 2026). A benign or malignant brain and spinal cord tumor that arises from glial cells (astrocytes, oligodendrocytes, ependymal cells). "However, little work has been done to elucidate the role of SEMA4G in glioma." (PMID 31921517, 2020). "From these genes, 8 were identified as independent prognostic factors for glioma (FGFR1, FLT3, VTN, NR2C1, SEMA4G, CFP, S100P, CHGB)." (PMID 41596318, 2026). "Furthermore, the roles of the IGRPS genes NR2C1, SEMA4G, CFP, and CHGB in gliomas and other cancers are uncharacterized." (PMID 41596318, 2026). "The role of other genes (NR2C1, SEMA4G, CFP, CHGB) included in IGRPS has not been elucidated in gliomas and other tumors." (PMID 36676646, 2022). "Currently, there is no study revealing the role of SEMA4G and CRTAC1 in gliomas." (PMID 31921517, 2020).
ovarian carcinoma (2 papers, 2019 to 2025). A malignant neoplasm originating from the surface ovarian epithelium. "In a similar study with the GeCKO library in the A2780 and SKOV3 ovarian cancer cell lines, ZNF587B, TADA1, SEMA4G, POTEC and USP17L20 were identified as candidate genes; among these, loss of ZNF587B and SULF1 gene expressions were associated with cisplatin resistance." (PMID 40242936, 2025).
asthma (1 paper, 2022). "For SEMA4G, the most important pathways enriched in the positive and negative correlative groups were ‘ribosome’, ‘allograft rejection’, ‘asthma’, ‘autoimmune thyroid disease’, ‘graft versus host disease’, and ‘systemic lupus erythematosus’." (PMID 35299740, 2022).
colorectal cancer (1 paper, 2020). A primary or metastatic malignant neoplasm that affects the colon or rectum. "It means that SEMA4G might be a tumor suppressor gene related to colorectal cancer." (PMID 31921517, 2020). "A low-expression of SEMA4G was detected in colorectal cancer tissues compared with normal tissues." (PMID 31921517, 2020).
glaucoma (1 paper, 2023). Increased pressure in the eyeball due to obstruction of the outflow of aqueous humor. "Of most significant coding variants associated with increased risk of glaucoma medication non-adherence, rs2272487 (CHCHD6), rs7975 (GSTZ1), and rs11591349 (SEMA4G) were identified by MPR80." (PMID 36982708, 2023).
melanoma (1 paper, 2021). A malignant, usually aggressive tumor composed of atypical, neoplastic melanocytes. "At protein level, several semaphorins, plexins and neuropilins have been detected in tissue cancer available in the database, including melanoma, except for Sema4A, Sema4F, Sema4G, Sema6B, plexinA4, plexinB3 for which melanoma specimens resulted weakly positive or prevalently negative." (PMID 33858502, 2021).
neuroblastoma (1 paper, 2020). Neuroblastoma (NB) is the most common solid, extracranial childhood tumor. "While Pea3 upregulates transcription of Sema3D and represses Sema5B, for example, Erm and Er81 upregulate Sema5A and Er81 regulates Unc5C and Sema4G while repressing EFNB3 in SH-SY5Y neuroblastoma cells." (PMID 33097800, 2020).
tumor (4 papers, 2019 to 2024). "SEMA4G levels were enriched in classical tumours while the expression of SEMA3A, SEMA3C and SEMA3F was significantly enriched in basal-like PDAC." (PMID 38670629, 2024). "Similarly,semaphorin 4G (SEMA4G, which has been suggested as tumor suppressor gene forcolorectal cancer) is downregulatedwith PROL1 overexpression (Log2FC = –4.8,p-value, 9 × 10−18) and isupregulated with PROL1 knockout (Log2FC = 2.6,p-value, 1.2 × 10−13)." (PMID 35547856, 2022). "In addition, five other genes, including TBPL1, USP28, NRG3, PPM1L, and RGR, were regulated by eRNAs expressed only in LGG tumor tissue; whereas SEMA4G was regulated by LGG-specific seRNAs." (PMID 35299740, 2022).
infection (1 paper, 2015). The state of being infected such as from the introduction of a foreign agent such as serum, vaccine, antigenic substance or organism. "Pattern "Virulent" includes 14 genes whose expression levels were not changed after infection with heat-inactivated MTB H37Rv or the attenuated vaccine strain BCG (e.g. MAP3K4, SEMA4G, BTG1), and only one of these also belongs to the pattern "Virulent" at 18 hours post-infection." (PMID 26586179, 2015).
SEMA4G also shares sentences with these, for which no sentence is quoted: cancer (2 papers); autoimmune thyroid disease (1); bladder cancer (1); lung adenocarcinoma (1); lymph node metastasis (1); pancreatic cancer (1); sarcopenia (1); systemic lupus erythematosus (1).